MMP2 (matrix metallopeptidase 2)
Diseases named in the same sentence as MMP2 in open-access papers (continued):
Sharing a sentence is not in itself a finding about the gene and the disease.
tumor (continued). "Indeed, over-expressed levels of MMP2 and MMP9 have been found in the tumor microenvironment." (PMID 28335259, 2016). "Therefore, it indicates that grifolin may impede metastatic tumor cells adhesion and migration through inhibition of CD44 and MMP2 expression and function as well." (PMID 27626695, 2016). "For SAS cells, the gene expression of MMP2, MMP9 and MMP14 in ALG-CS was significantly higher than that in ALG (for MMP2 P = 0, for MMP9 P = 0.04634, for MMP14 P = 0.00194), which indicated that ALG-CS could further enhance MMP gene expression in tumor cells compared with ALG." (PMID 27432752, 2016). "Importantly, KDM1A exerts these effects by epigenetically silencing TIMP3 transcription, which in turn increases MMP2 expression in the extracellular matrix (ECM) and JNK phosphorylation in the cytoplasm of tumor cells, thus contributing to cell invasion and migration in NSCLC." (PMID 27058897, 2016). "Thus, miR-29c could serves as a tumor metastasis suppressor, which negatively controls the cancer metastasis via targeting many molecules including Sp1, GNA13, PTP4A, integrin β1 and MMP2." (PMID 27829234, 2016). "MMP-2/9 have the natural function of cleaving the extracellular matrix, which is rarely required in healthy tissue, but since tissue reconstruction is needed around fast-growing tumors, the presence of MMP-2/9 is said to be related to the presence of invasive tumor tissue." (PMID 25985157, 2015). "Neither MMP2 nor MMP-9 activity was detected in tumor cells." (PMID 25885552, 2015). "However the differential expression of MMP2 by tumour cells does not appear to reflect the expected metastatic properties of these cells since metastatic MDA-MB-231 cells express little or no MMP2 and MMP9 in the extracellular medium." (PMID 26284589, 2015). "While ACPPD-Gd is relatively selective for MMP-2 and MMP-9, it is a generic contrast agent to any tissue that overexpresses those MMPs, particularly cancer, since MMPs are abundantly expressed in virtually all tumor lines during various stages of malignant progression and metastases." (PMID 26336058, 2015). "In contrast to MMP2, maspin is one of the classic tumor suppressor genes, and the opposite changes observed for ATF3 versus maspin expression suggest that the function of ATF3 opposes that of maspin, with ATF3 having a tumor-promoting role that is opposite to that of maspin." (PMID 25872784, 2015). "LIFr may or may not have effects on MMP2 mediated tumor progression depending on the cell types evaluated." (PMID 26329521, 2015). "Additionally, we examined whether the expression of the invasion proteins MMP-2 and MMP-9 was suppressed by blocking mTOR signaling in secondary NPC tumors and whether tumor sizes and weights were also affected." (PMID 26202311, 2015). "However, clinical utility of serum Ang-2 and MMP-2 and tumor HIF-1α was not addressed at this time and would need to be further evaluated and demonstrated." (PMID 25100134, 2014). "In addition, expression of MMP-2 and MMP-9 in tumor tissues was markedly enhanced by MVs." (PMID 24797571, 2014). "Also, there is evidence in PDAC that MMP-2 activation in conjunction with higher expression of alphaVbeta3 integrin had a significant correlation with lymph node metastasis rather than tumor size, or other prognostic factors." (PMID 24587996, 2014). "Besides, it was reported that BRG1 could promote MMP2 and MMP9 expression in some human tumor cells." (PMID 25304030, 2014). "Notably, MMP-2 and MMP-9 are important for tumor invasion and angiogenesis." (PMID 24520272, 2014). "Additionally, our results show the tumor stage, nodal involvement, presence of distant metastases, and tumor resectability, but not serum MMP-2 nor TIMP-2 as the significant prognostic factors in CRC patients in univariate analysis." (PMID 24395652, 2014).
tumor (continued). "A previous study revealed four important cancer invasion-related genes, MMP-1, MMP-2, EGFR and COX-2, in a variety of human cancers, including GC, which may manipulate the migration of tumour cells and the formation of new tumours by facilitating the release of tumour cells into the circulation." (PMID 23833643, 2013). "Blocking MMP-2 and MMP-9 with MMP inhibitors or antibodies against MMP-2 or/and MMP-9 partially rescues the invasion and metastasis effects thus providing direct evidence for the role of astrocyte-secreted MMP-2 and MMP-9 in tumor invasion and brain metastasis." (PMID 24324647, 2013). "We present a cross-sectional cohort study of the expression of HER-2 and MMP-2 in bone marrow micrometastasis detected in bone marrow biopsies and compare the effect of androgen blockade on HER-2 and MMP-2 expressions in tumor and surrounding stromal cells with that of men without androgen blockade." (PMID 23766685, 2013). "MI, PI, MMP-2 mRNA and tumor weight had negative correlation with PER1 mRNA expression." (PMID 23405233, 2013). "Given the role of MMP-2 in extracellular matrix degradation and growth factor/cytokine processing, we tested whether osteoblast derived MMP-2 contributed to the vicious cycle of tumor progression in the bone microenvironment." (PMID 22238668, 2012). "In conclusion, this study showed that EMMPRIN played an important role in the invasion of SACC-LM cells through functionally mediating the expression of MMP-2 and MMP-9 both in tumor and stromal cells, and its antibody could effectively inhibit SACC-LM cells adhesion and invasion in vitro." (PMID 22200897, 2012). "Also, tissue sections were stained with MMP-2, -9, -11, -14 and TIMP-2 antibodies, and immunoreactivity location, percentage of reactive area and intensity were determined at the invasive front and at the tumor center." (PMID 23300781, 2012). "We observed that the addition of the neutralizing TGFβ antibody to the MMP-2 null osteoblast conditioned media had no impact on tumor survival, while the addition of recombinant MMP-2 to conditioned media from MMP-2 null primary osteoblasts rescued the tumor survival phenotype." (PMID 22238668, 2012). "In addition, we demonstrated that CD44 blocking antibody could block MMP-2 and MMP-9 secretion as well as tumor invasion in MCF-7/CD44st cells." (PMID 21749678, 2011). "Given that expression of IL-6, IL-8, MMP2, and VEGF increased in parallel with STAT3 and AKT activation in HCC cells treated with IL-17, STAT3, and AKT signaling may play important roles in inducing these proinvasive factors and hence tumor progression." (PMID 22171994, 2011). "In conclusion, our results suggested that the IL-17 mediated tumor-promoting role involved a direct effect on tumor cells through IL-6 induction by activating the AKT pathway; IL-6 in turn activated JAK2/STAT3 and up-regulated proinvasive factors IL-8, MMP2, and VEGF both in vitro and in vivo." (PMID 22171994, 2011). "Our previous observation that a fraction of HLA-A*0201 tumor cell lines lacking αvβ3 integrin expression and secreting MMP-2 protein was not recognized by the specific T cell clone, led us to suggest that the amount of unfolded form or DRiP containing the epitope are low in these cells." (PMID 20689590, 2010). "In order to determine whether the endogenous presentation of MMP-2 by tumors cells is similarly affected by the removal of disulfide bonds, we used HLA-A2 tumor cell lines that fail to cross-present MMP-2 due to their lack of αvβ3 integrin." (PMID 20689590, 2010). "Moreover, another report also indicated that lipocalin 2 was possibly involved in invasion of tumor cells by regulating activity of MMP-9 and MMP-2, but was not apparently related with division and proliferation of tumor cells in SHEEC." (PMID 19077278, 2008).
tumor (continued). "During our recent investigations to understand the mechanisms by which PTTG1 is involved in tumor angiogenesis and metastasis, we performed transient and stable transfections of HEK293 cells with PTTG1 cDNA and studied the expression and secretion of matrix metalloproteinase (MMP)-2." (PMID 19014669, 2008). "Accordingly, it has been previously demonstrated that the activity of MT1-MMP and of the active form of MMP-2 in the medium of human endothelial cells was decreased in presence of EGCG and that the consequence of the inhibitory activity of metalloproteases was a blocking of tumor cell invasion." (PMID 18426555, 2008). "Pretreatment of conditioned medium with MMP-2-specific antibody significantly decreased these effects, suggesting that PTTG may contribute to tumor angiogenesis and metastasis via activation of proteolysis and increase in invasion through modulation of MMP-2 activity and expression." (PMID 17096843, 2006). "However, in our system, siRNAs targeting MMP-2 or -9 or other MT-MMPs did not influence tumor invasion of collagen matrices." (PMID 17156449, 2006). "Since levels of TIMPs have not been determined in this study, one could speculate that the increased levels of MMP-2 and -9 in tumour will have no actual biological consequence in the in vivo situation because of endogenous inhibition." (PMID 12085179, 2002). "Comparison between primary tumours with and without synchronous liver metastasis showed that tumours with liver metastasis (TxNxM1) had significantly lower activity of both active MMP-2 (P=0.005) and proMMP-2 (P=0.009) than those without liver metastasis (TxNxM0)." (PMID 12085179, 2002). "Besides MFcells, the MMP-2 and/or MMP-9 mRNAs were expressed by some stromal cell populations(microvascular endothelial cells, fibroblasts, macrophages), suggesting that these cells cooperatein the process of tumor invasion." (PMID 11097203, 2000). "Additionally, it inhibits matrix metalloproteinases Matrix Metalloproteinase-2 (MMP-2) and Matrix Metalloproteinase-9 (MMP-9), reducing invasiveness, and decreases reactive oxygen species (ROS) production, thereby limiting oxidative stress–induced tumor progression." (PMID 40978472, 2025). "In addition, MMP-2 and MMP-9 promote tumor progression by modulating the tumor microenvironment through the activation of chemokines and proinflammatory cytokines, which recruit immune cells that may support tumor growth and survival." (PMID 40563423, 2025). "In addition, it inhibits metastasis by downregulating the metalloproteinases MMP-2 and MMP-9, essential in the degradation of the extracellular matrix, and by disrupting the CXCL12/CXCR4 chemokine axis involved in the epithelial–mesenchymal transition and tumor cell migration." (PMID 40572668, 2025). "We found that the expressions of MMP-14, MMP-19 and MMP-2 were upregulated in BCL individuals compared to CC, during which fibroblasts and myeloid cells displayed abundant MMP expression, indicating that the MMPs gene set could participate in inhibits tumor progression of CC." (PMID 39247608, 2024). "However, the expression of MMP-2 in recurrent tumour tissues was not significantly different from that in primary tumour tissues, suggesting that MMP-2 expression may differ individually in recurrent ACP." (PMID 38594611, 2024). "However, the expression of MMP-2 in all tested tumor cells did not seem to differ." (PMID 38256960, 2024). "Additionally, Wnt-1, β-catenin, cyclin-D1, MMP2, and MMP9 as well as Ki-67 levels were higher in tumor cells of the model + sh-SOST group than that of the model + sh-NC group, demonstrating that SOST suppression was capable of activating Wnt/β-catenin signaling in ocular orthotopic tumor models." (PMID 35785219, 2022). "Therefore, MMP2 and/or MMP9 might be involved in tumour cell invasion." (PMID 35954423, 2022).
tumor (continued). "In addition, expression of molecules involved in ECM remodeling such as several metalloproteinases (MMP2, MMP9, MMP10 and MMP13), serine protease (PLAU) collagens, fibronectins and integrins indicate that functional EMT transition and metastasis take place within the tumor microenvironment." (PMID 34946170, 2021). "In addition, silencing of SPNS2 increased MMP2 and MMP9 expression, while overexpression of SPNS2 decreased the MMP2 and MMP9 expression, which could degrade the extracellular matrix and stimulate tumor invasion and metastasis." (PMID 34249729, 2021). "Moreover, studies have reported that tumor constituent cells regulate the biomechanical properties of the ECM, decreases the ECM stiffness by increasing the matrix metalloproteinase (MMPs) such as MMP2, MMP9, MMP13, and MMP14 enabling them to metastasize to distant tissues." (PMID 34613483, 2021). "Moreover, as these tissue arrays do not provide information about neoadjuvant treatment, chemotherapy and radiotherapy, we could not perform a detailed analysis on NGF and MMP-2 levels in relation to the tumor stage." (PMID 34283074, 2021). "In the tumor tissue of LF group, we observed that the expression of MMP-9 was higher than that of control group in liver tissue while there was no statistical difference in the MMP-2 expression between two groups, which may be related to the characteristics of tumor cell lines." (PMID 34819565, 2021). "Tumor-derived EVs deliver ECM-MMPs inducers which can contribute to matrix degradation in different diseases: For instance, EVs derived from ovarian cancer contain high levels of MMP-2, MMP-9, and urokinase-type plasminogen activator proteinases that could degrade the ECM104." (PMID 34446834, 2021). "Multiple tumour types have been shown to be markedly hypoxic, which may favour a pro-tumorigenic neutrophil phenotype—the increased release of neutrophil MMP-9 can promote cancer growth by enabling angiogenesis, whilst neutrophil proteases can facilitate tumour cell invasion by activating pro-MMP-2." (PMID 32053993, 2020). "We could see that about half MMPs are highly expressed in tumor tissues as compared with normal tissues, including MMP9, MMP10, MMP11, MMP12, MMP15, MMP25, MMP26 (all, P<0.05), while some other MMPs decreased in tumor tissues, including MMP2, MMP14, MMP16, MMP24, MMP28(all, P<0.05)." (PMID 32669958, 2020). "The expression of PCNA, VEGF, MMP‐2, and MMP‐9 in Diet I+NDEA and Diet II+NDEA groups was significantly lower than in the NDEA group (p < 0.01 or p < 0.05), indicating that Diet I and Diet II could inhibit cancer proliferation and affect tumor neovascularization, invasion, and metastasis." (PMID 30680188, 2019). "Additionally, in statistical analyses, MMP-2 in tumor-stroma (T-S), MMP-9 (T-S), TIMP-1 (T-S), and TIMP-2 (T-S) variables were introduced in order to determine the differences in the expression of metalloproteinases and their inhibitors between the tumor and stroma." (PMID 31223594, 2019). "Likewise, the plant polyphenol downregulated expression of MMP-2, integrin receptors, focal adhesion kinase (FAK), and MT1-MMP to almost background levels in laryngeal squamous carcinoma cells, leading to significantly reduced invasive potential of the tumor cells." (PMID 29890744, 2018). "Moreover, the expression of LATS2 and p-YAP1(Ser127) increased, whereas YAP1, Axl, c-Myc, Cyr61, MMP-2 and MMP-9 expression levels were simultaneously decreased in amlexanox-treated group relative to the DMSO-treated group, which was consistent with the subcutaneous tumor tissues results." (PMID 29048430, 2017). "Moreover, CAFs may have not expressed high amounts of MMP2 since most CAS areas collected in this study were from areas inside the tumour mass and not at its border, where most of the remodelling processes are thought to take place." (PMID 28531107, 2017).
tumor (continued). "As our in vitro studies revealed expression changes of mesenchymal proteins, SNAIL and vimentin, and of MMP-2 and MMP-9 on cancer cells treated with the combination of metformin and selumetinib, we also investigated whether the combination therapy blocks tumour metastatic behavior in vivo." (PMID 26673006, 2016). "EMT is considered as a major mechanism involved in the dissemination of tumor cells in HCC, However, our current data showed that ApoA-1 treatment might inhibit CTC formation via EMT-independent mechanism, in which the expressions of MMP2, MMP9, and VEGF were strongly down-regulated." (PMID 27683106, 2016). "Furthermore, our present finding showed that, 17-AAG inhibited LAC cell growth and invasion with the decreased expression of Ki-67 and MMP-2, suggesting that LATS1/YAP signalling might mediate 17-AAG suppression of tumour growth and invasion via regulation of Ki-67 and MMP-2 expression in LAC cells." (PMID 25712415, 2015). "Moreover, the expression of E-cadherin (CDH1), a negative-related protein for tumor invasion, was clearly reduced, and two positive-related proteins for tumor invasion and metastasis, MMP-2 and MMP-9, were increased in expression in the IgGhigh MDA-MB-231 cells." (PMID 26472025, 2015). "Furthermore, several investigations reported that transforming growth factor-beta 1 (TGF-β1), produced in the tumor microenvironment, could be a strong mediator of pancreatic cancer cell invasion, metastasis, and angiogenesis by upregulating VEGF, MMP-2, and uPA secretion." (PMID 25295247, 2014). "Tumour buds may have a role in ECM degradation, a hypothesis supported by increased immunohistochemical expression of proteins such as matrix metalloproteinases MMP-2 and MMP-9, and urokinase plasminogen-activator receptor (uPAR) in high-grade tumour-budding cases." (PMID 22531633, 2012). "However, whether MMP-2, in turn, contributes to αvβ3 integrin-mediated tumor cell migration is not clear." (PMID 22848537, 2012). "The negative correlation between MMP-2 expression and TILs, including NK cells, DCs, neutrophils, macrophages, and CD8+ T cells, further emphasizes the role of MMP-2 in modulating the tumor immune microenvironment." (PMID 40611940, 2025). "The present study provides the first evidence of a positive correlation between MMP-2 expression and PD-L1 level in COAD, along with a negative correlation with tumor-infiltrating lymphocytes (TILs)." (PMID 40611940, 2025). "Zymography data showed that MMP-2 and MMP-9 expression was down-regulated M13SV1-EGFP-Neo treated with minocycline, but not in HS578T-Hyg cells or M13HS-2 and M13HS-8 tumor hybrids." (PMID 40471394, 2025). "When exposed to the high expression of MMP2 in tumor cells, the PEG shell was removed, changing the zeta potential from negative to positive, promoting tumor cells uptake and preventing non-specific uptake by healthy cells." (PMID 39337266, 2024). "Our in vivo analysis of orthotopic tumours with picrosirius red staining also revealed a decrease in the ECM, and inhibiting MMP2 or MMP9 alone was not as effective as the MET inhibitor or GW." (PMID 39025845, 2024). "Specifically, the non-competitive inhibition of MMP2, MMP14 and MMP13 using potassium ferricyanide has shown in some studies significant reductions in tumor growth in a murine model of breast cancer lung metastases with VCO growth." (PMID 38255995, 2024). "Given that in non-angiogenic tumors a greater overexpression of MMP2 and MMP14 has been observed, it is of interest to inhibit these MMPs in order to reduce the aggressiveness of non-angiogenic tumor growth." (PMID 38255995, 2024). "Knockdown of AAK1 substantially suppressed tumor growth, tumor weight, as well as the expression of AKK1, Notch3, GLS, MMP-2, MMP-9, and Ki-67 percentage." (PMID 38169546, 2024).